ROR2 (ROR family WNT receptor 2)
Description:
Tyrosine-protein kinase receptor which may be involved in the early formation of the chondrocytes. It seems to be required for cartilage and growth plate development (By similarity). Phosphorylates YWHAB, leading to induction of osteogenesis and bone formation. In contrast, has also been shown to have very little tyrosine kinase activity in vitro. May act as a receptor for wnt ligand WNT5A which may result in the inhibition of WNT3A-mediated signaling.
Synonyms: NTRKR2; BDB; BDB1; RRS1
Tractability: Small molecule: it has a high-quality binding pocket; it belongs to a druggable protein family. Antibody: its Gene Ontology location is reachable by antibodies, with high confidence; UniProt places it where antibodies can reach, with medium confidence; UniProt predicts a signal peptide or a membrane-spanning region. PROTAC: ubiquitination databases record sites on it; its protein half-life has been measured.
Target class: Kinase; Enzyme; Protein Kinase; TK protein kinase group
Gene: Protein-coding gene on chromosome 9 (91,563,091 to 91,950,240, reverse strand). Ensembl gene ENSG00000169071.
Subcellular location: Cell membrane
Pathways (Reactome):
Signal Transduction: PCP/CE pathway; WNT5A-dependent internalization of FZD2, FZD5 and ROR2
Gene Ontology:
Molecular function: mitogen-activated protein kinase kinase kinase binding; protein binding; protein tyrosine kinase activity; Wnt-protein binding; coreceptor activity; transmembrane receptor protein tyrosine kinase activity; ATP binding; protein kinase activity
Biological process: positive regulation of cell migration; signal transduction; cell surface receptor protein tyrosine kinase signaling pathway
Cellular component: axon; clathrin-coated endocytic vesicle membrane; plasma membrane; receptor complex
Genetic constraint (gnomAD): Loss-of-function variants: 33 observed, 81.28 expected, observed/expected ratio (o/e) 0.41, 90% interval 0.31 to 0.54. The upper end of that interval is the gene's LOEUF score, 0.54, which puts it in group 2 of 6, group 1 being the genes least tolerant of losing a copy. Missense variants: 1,204 observed, 1,332 expected, observed/expected ratio (o/e) 0.9, 90% interval 0.86 to 0.95. Synonymous variants: 579 observed, 563.52 expected, observed/expected ratio (o/e) 1.03, 90% interval 0.96 to 1.1.
Homologues: Orthologues: chimpanzee ROR2 (99% identical), macaque ROR2 (98% identical), pig ROR2 (93% identical), rabbit ROR2 (93% identical), mouse Ror2 (92% identical), guinea pig ROR2 (92% identical), dog ROR2 (91% identical), rat Ror2 (91% identical), tropical clawed frog ror2 (80% identical), zebrafish ror2 (70% identical). Paralogues in human: ROR1 (57% identical), NTRK2 (22% identical), MUSK (22% identical), NTRK1 (21% identical), ROS1 (21% identical), NTRK3 (21% identical), INSR (19% identical), EPHB3 (18% identical), IGF1R (18% identical), EPHB1 (18% identical), EPHA6 (18% identical), EPHB4 (18% identical), and 41 more.
Diseases named in the same sentence as ROR2 in open-access papers:
ROR2 is named in the same sentence as 144 diseases in open-access papers, as found by Europe PMC text mining. Sharing a sentence is not in itself a finding about the gene and the disease. The quoted sentences say what the papers report.
melanoma (37 papers, 2010 to 2025). A malignant, usually aggressive tumor composed of atypical, neoplastic melanocytes. "Research has shown that hypoxia can induce a switch in melanoma cells from a receptor tyrosine kinase-like orphan receptor 1 (ROR1)+ to a more invasive ROR2+ phenotype, which is associated with resistance to BRAF inhibitors." (PMID 40867277, 2025). "Unlike what was described in other cancers, the dual role of ROR2 in melanoma is associated with the regulation of different biological processes." (PMID 36127680, 2022). "To investigate the role of ROR2 in melanoma cell proliferation we used both gain- and loss-of-function approaches." (PMID 34774050, 2021). "By using both gain- and loss-of-function approaches we demonstrated that ROR2 strongly inhibits Akt phosphorylation in four melanoma cell lines." (PMID 34774050, 2021). "It was shown that murine Ror2 contributed to migration and metastasis and that ROR2 expression associates with a more invasive phenotype and is necessary for the Wnt5A-mediated metastasis of melanoma cells." (PMID 34774050, 2021). "In cancers such as in melanoma, breast, and prostate tumors among others, elevation of the Ror2 protein has been linked to increased cell migration resulting to tumor progression and chemo-resistance." (PMID 32484838, 2020). "Recently, ROR1 and ROR2 co-receptor upregulation was associated to the two different melanoma states: proliferative and invasive." (PMID 31921125, 2019). "Since the results above show that ROR2 inhibits melanoma cell proliferation and tumor growth, we wanted to determine whether ROR2 expression in human melanomas associates with tumor features related to proliferation." (PMID 34774050, 2021). "ROR2 upregulation plays oncogenic roles in renal cell carcinoma, osteosarcoma, breast cancer, and melanoma." (PMID 41470892, 2025). "In the context of the regulatory relationship between ROR2 and Akt, studies have indicated that ROR2 can modulate Akt phosphorylation through activation or inhibition in different cancers, including melanoma, breast cancer, myeloma, and osteosarcoma." (PMID 38632356, 2024). "This Wnt5A/ROR2 signalling cascade promotes filamin cleavage by calpain 1 which in turn leads to increased melanoma cell motility." (PMID 38958472, 2024). "It has also been shown that filopodia formation mediated by ROR2 is required for WNT5A-induced cell migration in human melanoma cell lines further supporting our observation of a role for direct transport of ROR2 in inducing migration in AGS cells." (PMID 37722040, 2023). "This would enable assessment of the effects of long-term ROR2 loss, to further evaluate the extent to which ROR2 is required for the vascular phenotype and VEGF dependency of BRAF mutant melanoma." (PMID 36539575, 2023). "Of 61 genes concordantly deregulated in clinical melanomas ROR2 was one of the most upregulated by BRAFV600E." (PMID 36539575, 2023). "Next, VEGF secretion was tested in culture medium conditioned by melanoma cells transfected with ROR2 or control siRNA." (PMID 36539575, 2023). "We have shown that ROR2 impairs cell cycle progression and consequently inhibits the proliferation of melanoma." (PMID 36127680, 2022). "Recent findings from our group have established that ROR2 can play this dual role simultaneously in melanoma cell lines." (PMID 36127680, 2022). "In the present article, ROR2 is proposed to be a major driver of “phenotype switching” in melanoma that can tilt the cellular behavior toward proliferative or invasive phenotypes." (PMID 36127680, 2022). "Regarding ROR2, overexpression of ROR2 increases the metastasis ability of B16 murine melanoma cells, and inhibition of Src is critical for the ROR2-mediated cell migration upon Wnt5a treatment." (PMID 35625853, 2022). "Since both proliferation and invasion are critical at different disease stages, ROR2 would play different roles in melanoma initiation, promotion, and progression." (PMID 36127680, 2022).
melanoma (continued). "Overexpression of ROR2 in osteosarcoma, melanoma and breast cancer has been proposed to play a role in cell migration, cell proliferation and spatiotemporal control of tumor cell heterogeneity." (PMID 35246138, 2022). "We have recently observed that ROR2 plays multiple and somewhat contradictory roles in melanoma where it impairs cell proliferation but promotes migration, EMT and chemoresistance." (PMID 36127680, 2022). "ROR2 has been involved in the Wnt pathway in various cancer systems and in hypoxia-induced plasticity in melanoma cells." (PMID 34359798, 2021). "In response to a variety of environmental stimuli, the extracellular ligand WNT5A interacts with ROR2 and Frizzled (Fzd)-family receptors, resulting in AP-1 activation and subsequently promotes melanoma cell invasion." (PMID 34604096, 2021). "The tumor-suppressive functions of ROR2 are also supported by the observation that high ROR2 levels correlated with a better prognosis of primary melanomas and is upregulated in patients showing transcriptomic signatures of good prognosis." (PMID 34774050, 2021). "The role of ROR2 in melanoma patients was assessed by analysis of clinical data from the Leeds Melanoma Cohort." (PMID 34774050, 2021). "Previous investigations have established that ROR2 promotes cancer progression in melanoma by facilitating invasion and metastasis." (PMID 34774050, 2021). "We conclude that the expression of ROR2 slows down the growth of primary tumors and contributes to prolonging melanoma survival." (PMID 34774050, 2021). "We next performed xenotransplantation experiments to evaluate the role of ROR2 on in vivo melanoma growth." (PMID 34774050, 2021). "Altogether, these results indicate that by inhibiting cell proliferation ROR2 plays a protective role in primary melanomas since tumors expressing ROR2 remain thinner and have a better prognosis." (PMID 34774050, 2021). "Gain and loss-of-function strategies were applied to study the biological function of ROR2 in melanoma." (PMID 34774050, 2021). "We have demonstrated that ROR2 inhibits Akt activity in melanoma and consequently it alters the expression, activity, and localization of major components of the cell-cycle regulatory machinery." (PMID 34774050, 2021). "For instance, in melanoma ROR1 knockdown was followed by increased expression of ROR2 and WNT5A, while the knockdown of ROR2 stimulated ROR1 expression, confirming a reciprocal regulation." (PMID 33445713, 2021). "For example, in melanoma cells, ROR2-FLNA interaction is critical for WNT5A-induced JNK phosphorylation, cytoskeleton remodeling, and cell migration, and WNT5A-ROR2 binding induces calpain expression and its cleavage of FLNA leading to increased invasiveness." (PMID 33134326, 2020). "Upregulation of ROR2 in osteosarcoma, melanoma, renal cell carcinoma, chemoresistant ovarian cancer and the relationship with higher risk diseases defined it as a tumor promoter in early studies." (PMID 31878941, 2019). "ROR2 played as tumor promoter in renal cancer, chronic lymphocytic leukemia, malignant melanoma, whereas its high expression was shown to be related with better prognosis in patients with colorectal cancer, liver cancer, medulloblastoma and endometrial cancer." (PMID 31878941, 2019). "ROR2 is up-regulated in a lot of human tumors including osteosarcoma, melanoma, renal cell carcinoma, prostate carcinoma, colorectal cancer, squamous cell carcinomas of the head and neck, stromal tumors, and breast cancers." (PMID 29213214, 2017). "It has been shown that sustained or increased expression of Wnt5A and/or ROR2 affects the invasive properties of several types of tumor cell, including melanoma, osteosarcoma, renal cell carcinoma, prostate carcinoma, gastric cancer and pancreatic cancer." (PMID 28536612, 2016).
melanoma (continued). "Previous studies showed that Wnt5A requires ROR2 expression to mediate the migration of cells during mammalian palate development and that increased expression of Wnt5A led to increased melanoma cell motility." (PMID 28536612, 2016). "ROR1 and ROR2, receptors associated with WNT5A signaling, have also been implicated in WNT5A-induced phenotype switching, with ROR2 expressing melanoma cells demonstrating a more invasive phenotype." (PMID 26393652, 2015). "ROR2 was found to be highly expressed in osteosarcoma, renal cell carcinomas, melanoma, colon cancer, squamous cell carcinoma of the head and neck, and breast cancer." (PMID 26328272, 2015). "Recent experiments have confirmed that the Wnt5a-ROR2 signaling cascade is crucial in the aggressive course of osteosarcoma, melanoma, and renal cell carcinoma cell lines." (PMID 26305508, 2015). "ROR2 has pro-tumorigenic effects in renal cell carcinoma, osteosarcoma and melanoma cell lines in in vitro and xenograft experiments." (PMID 26305508, 2015). "In parallel, they validated these findings in vivo by showing an increased response to PLX4720 therapy in ROR2 siRNA-treated PLX-resistant 1205 LU melanoma cells, compared to controls." (PMID 26393652, 2015). "Recent work in melanoma has suggested a role for Ror2 in altering the cancer phenotype toward more invasive characteristics in congruence with our findings presented here." (PMID 25542006, 2014). "Another way to target hypoxia pathways is to target the Wnt5A/ROR2 axis that could improve the efficacy of treatments like vemurafenib in melanoma patients." (PMID 40867277, 2025). "By assuming the proposed role, ROR2 would have a dual impact on melanoma." (PMID 36127680, 2022). "Even in melanoma, targeting ROR2 might provide a greater proliferative capacity to melanoma cells that already spread to secondary sites, thus increasing the tumor burden." (PMID 36127680, 2022). "ROR2 is involved in the formation of melanoma in humans, suggesting a role in melanin formation." (PMID 34220935, 2021). "In addition, whereas ROR2 expression is a marker of good prognosis (this manuscript), ROR1 was shown to correlate with poor melanoma survival, further supporting the opposite function of both ROR1 and ROR2 in melanoma." (PMID 34774050, 2021). "In response to hypoxia, ROR1-expressing melanomas adopt a ROR2-positive invasive phenotype." (PMID 34604096, 2021). "Interestingly, ROR2 was expressed in only 20 of 48 of primary melanoma cases, while all of the investigated visceral or subcutaneous metastases (48/48) stained positive." (PMID 33445713, 2021). "Altogether, these results demonstrate that ROR2 strongly regulates the level of expression of proteins regulating cell-cycle progression which explains the observed effects of ROR2 in the cell-cycle distribution and proliferation of melanoma cells." (PMID 34774050, 2021). "This has since been confirmed in several solid tumor entities in which knockdown of ROR2 resulted in decreased migration and/or invasion, e.g., in mesothelioma, melanoma, renal cancer, breast cancer, ovarian cancer, prostate cancer, leiomyosarcoma, gastrointestinal stroma tumors, and osteosarcoma." (PMID 33445713, 2021). "Consequently, cancer cells with reduced expression of ROR1 or ROR2 were characterized by a significantly impaired potential in forming metastases in mouse models of melanoma or breast cancer." (PMID 33445713, 2021). "However, data presented in this article reveal that ROR2 has a dual role since it also inhibits melanoma proliferation and tumor growth." (PMID 34774050, 2021). "WNT5A modulates melanoma cell behavior via multiple cell surface receptors/co-receptors, including ROR2 and Frizzleds, and downstream molecular targets, such as APT1, IL-6, and PKC-STAT3, which in turn affect various melanoma cell functions, including migration and invasion." (PMID 32033033, 2020).
melanoma (continued). "In addition, ROR2 promotes the Wnt-mediated signaling in several types of cancer, including melanoma and colon cancer." (PMID 32614787, 2020). "Interestingly, ROR2 is re-expressed in a wide range of adult cancers, such as prostate carcinoma, oral squamous cell carcinoma, melanoma, colorectal cancer, and osteosarcoma, playing significant roles in tumor cell metabolism, proliferation, invasion, and metastasis." (PMID 38632356, 2024). "It has also been reported that phenotype switching in melanoma is regulated by the Wnt signaling pathway and that Wnt5A-treated B16 melanoma cells acquire greater metastatic and invasive potential, an effect mediated by the orphan tyrosine kinase receptor ROR2." (PMID 36135194, 2022). "Based on western blot analysis of a panel of melanoma cell lines, cell lines A375 and UACC903, expressing low levels of ROR2, were selected for gain-of-function studies and stably transduced with an expression vector encoding human ROR2 or Empty vector as a control." (PMID 34774050, 2021). "Additionally, metastatic invasion was inhibited in ROR2-silenced melanoma cells in a mouse model." (PMID 26305508, 2015). "Similarly, ROR2 functions as a survival kinase that contributes to the resistance of HeLa cervical carcinoma cells to apoptosis, and it has been proposed as a target for melanoma and osteosarcoma therapy." (PMID 22073312, 2011). "Using whole transcriptome data derived from 703 primary melanomas from the Leeds Melanoma Cohort (LMC), we found that ROR2 level is highest in tumors at the T1 stage and significantly higher than tumors at the T4 stage." (PMID 34774050, 2021). "Studies in osteosarcoma, melanoma, CLL, breast, and renal cancer have claimed that ROR2 acts as an oncogene in these entities." (PMID 33445713, 2021). "To elucidate the molecular pathways responsible for the anti-proliferative role of ROR2 we first evaluated the effects of ROR2 on the PI3K/Akt pathway, a signaling cascade that is usually constitutively active in melanoma." (PMID 34774050, 2021). "The treatment of proliferative melanoma cells, expressing ROR1, with WNT5a induced ROR1 degradation, increased ROR2 expression and high invasiveness in vivo." (PMID 31921125, 2019). "ROR2, VANGL2, and DVLs were demonstrated to be involved in the WNT pathway, serving as pivotal regulators of proliferation, metastasis, and development of colon cancer, thyroid cancer, and melanoma." (PMID 39052013, 2024). "In melanoma, RNF43 has been found to inhibit cell invasion and reverse the resistance to BRAF V600E and MEK inhibitors by stimulating the ubiquitination and proteasomal degradation of VANGL2 and inhibiting ROR2 in vitro and in vivo." (PMID 37848933, 2023). "ROR2 depletion inhibited VEGF mRNA expression in isogenic BRAFV600E melanoma cells, but not in isogenic BRAFWT cells, nor in A375M and SKMEL28 cells that harbour an endogenous BRAFV600E mutation." (PMID 36539575, 2023). "Quantification of intracellular VEGF showed a reduction upon ROR2 depletion in isogenic BRAFV600E melanoma cells, but no significant change in isogenic BRAFWT cells or A375M and SKMEL28 cells." (PMID 36539575, 2023). "However, similar to other TKR important in melanoma such as AXL and EGFR, ROR2 does alter the expression of numerous proteins in melanoma and other cancers." (PMID 36127680, 2022). "LMC class 1, composed of thin melanomas with a good prognosis and absence of proliferation markers, displays higher ROR2 levels than LMC class 3, composed of thicker melanomas with poor prognosis and a highly proliferative profile." (PMID 34774050, 2021). "This suggests that activation of noncanonical WNT5A-induced signaling and ROR1 and ROR2 changes is indeed a part of the melanoma adaptation mechanism to vemurafenib." (PMID 34702444, 2021). "Unlike previous findings describing ROR2 as an oncogene in melanoma, we describe that ROR2 prevents tumor growth by inhibiting cell-cycle progression and the proliferation of melanoma cells." (PMID 34774050, 2021).
melanoma (continued). "Furthermore, by showing that knockdown of ROR2 can sensitize melanoma cells to PLX4720 therapy, they indicated a role for WNT5A in BRAFi resistance in melanoma cells." (PMID 26393652, 2015). "ROR2 is a component of the non-canonical WNT pathway, which has been implicated in the phenomenon of dynamic phenotype switching in which melanomas switch from a highly proliferative, non-invasive phenotype to a phenotype associated with invasion, increased motility and high metastatic potential." (PMID 36539575, 2023). "In the isogenic BRAFV600E and BRAFWT melanoma clones cultured under normoxia, differential ROR2 expression was again apparent, but HIF-1α protein was not detectable, suggesting that BRAFV600E acquisition did not promote ROR2 upregulation via HIF-1α stabilization." (PMID 36539575, 2023). "Given that ROR2 expression reportedly undergoes HIF-1α -mediated upregulation in hypoxia, we tested whether increased ROR2 expression and VEGF secretion in BRAFV600E melanoma cells resulted from HIF-1α stabilization." (PMID 36539575, 2023).